HDAC6 (histone deacetylase 6)
Diseases named in the same sentence as HDAC6 in open-access papers (continued):
Sharing a sentence is not in itself a finding about the gene and the disease.
polycystic kidney disease (3 papers, 2012 to 2025). A usually autosomal dominant and less frequently autosomal recessive genetic disorder characterized by the presence of numerous cysts in the kidneys leading to end-stage renal failure. "Thus, targeting HDAC6 to downregulate EGFR activity may provide a potential therapeutic approach to treat polycystic kidney disease." (PMID 23152903, 2012). "Thus, targeting HDAC6 to downregulate EGFR and also normalize EGFR localization may be a potential therapeutic approach to treat polycystic kidney disease." (PMID 23152903, 2012). "Thus, targeting HDAC6 to downregulate EGFR and its downstream targets as well as to normalize its localization from apical to basolateral may be a potential therapeutic approach for polycystic kidney disease." (PMID 23152903, 2012).
Renal cyst (3 papers, 2020 to 2021). A fluid filled sac in the kidney. "Dysregulation of HDAC6-mediated signaling commits the pathological progresses, such as cystic kidneys 12, neurological diseases 13 and cancers 14-16." (PMID 33162791, 2020). "Dysregulation of HDAC6 is taken account into several pathological developments, such as cystic kidneys 12, neurodegenerative diseases 13 and tumorigenesis 14-16." (PMID 33162791, 2020).
retinal degeneration (3 papers, 2011 to 2021). Degeneration of the retina. "HDAC6 knock-down in a Drosophila melanogaster model of SBMA exacerbated retinal degeneration and overexpression of HDAC6 decreased aggregate load and ameliorated retinal degeneration, effects that required HDAC6 catalytic activity." (PMID 21677773, 2011).
retinopathy of prematurity (3 papers, 2022 to 2025). A bilateral retinopathy characterized by neovascularization, scarring, retinal detachment, and eventually blindness. "Herein the authors show that overexpression of histone deacetylase 6 (HDAC6) in mice induces the typical pathological changes associated with retinopathy of prematurity (ROP), an eye disease affecting premature infants." (PMID 35619548, 2022). "Additionally, blocking HDAC6‐mediated cilium disassembly protects mice from retinopathy of prematurity (ROP)‐associated retinal defects." (PMID 38514901, 2024).
sarcoma (3 papers, 2021 to 2022). A usually aggressive malignant neoplasm of the soft tissue or bone. "Our results show the relevant role of HDAC6 in EWS and suggest the use of selective HDAC6 inhibitors as a novel therapeutic approach to treat this type of sarcoma." (PMID 34345016, 2021). "HDAC6 inhibitors have been shown to be of potential benefit in neurodegeneration in ALS, as they can restore histone acetylation levels and consequently slow down disease progression in a FUS (fused in sarcoma) mouse model of ALS." (PMID 35328416, 2022). "LINC00461 was inversely correlated with the survival of mice-bearing GBM and it was stabilized by the interaction between HDAC6 and RNA-binding proteins (RBPs) such as carbon catabolite repression—negative on TATA-less (CCR4-NOT) core exoribonuclease subunit 6 and fused in sarcoma." (PMID 35109908, 2022).
age-related macular degeneration (2 papers, 2015 to 2024). Age-related loss of vision in the central portion of the retina (macula), secondary to retinal degeneration. "Interestingly, G570, a dual targeting HDACi that inhibits HDAC6/heat shock protein 90, has been shown to inhibit retinal neovascularization and blue light-induced cell migration in age-related macular degeneration." (PMID 39281836, 2024). "Human neural retina concentrations of HDAC1, 2, HDAC5, HDAC6, and HDAC7 decreased in age-related macular degeneration (AMD)-affected donors and exhibited a greater decrease in AD-affected donors in comparison to age-matched control neural retinas." (PMID 25962138, 2015).
anaplastic astrocytoma (2 papers, 2021 to 2022). "Over-expressed HDAC6 showed FCs of 3.22 and 2.61 for GBM (n = 81) (p = 8.88E-13) and anaplastic astrocytoma (n = 19) (p = 2.34E-06) groups, respectively." (PMID 34540896, 2021). "The database search returned a 2.608-fold increase in HDAC6 mRNA expression in anaplastic astrocytoma compared with normal tissues (p = 2.34E-6)." (PMID 35359455, 2022).
Arrhythmia (2 papers, 2024 to 2025). Any cardiac rhythm other than the normal sinus rhythm. "Third, we could not create atrial cardiomyocyte‐specific deletion and overexpression of HDAC6 mice to explore the role of HDAC6 in MI‐induced AR and arrhythmia in mice." (PMID 40377174, 2025).
astrocytoma (2 papers, 2008 to 2020). "The highest level of mRNA was observed for HDAC9a and HDAC9b, with relative expression reaching values above 100 for normal brain tissue and grade I astrocytomas; however, HDAC6 and HDAC7 showed levels of expression comparable with those of class I (approximately 1.0 and 3.0)." (PMID 18713462, 2008).
autoimmune (2 papers, 2017 to 2021). "It is known that inhibition of HDAC6 enhances the suppressive activity of Treg cells in inflammation and autoimmunity." (PMID 28673326, 2017). "The inhibition of HDAC6 was reported to enhance the suppressive activity of regulatory T cells (Treg cells) in inflammation and autoimmunity." (PMID 28673326, 2017).
bladder urothelial carcinoma (2 papers, 2024). "Studies have revealed that inhibition of HDAC6 results in apoptosis induction, which is in agreement with our result showing the reduced activity of HDAC6 by TSC and apoptosis induction in urothelial bladder cancer cell line J82." (PMID 38675387, 2024).
brain cancer (2 papers, 2013 to 2019). A primary or metastatic malignant neoplasm affecting the brain. "HDAC6 is located on the Xp11 chromosome, and HDAC6 seems to be found in the brain, breast, colon, ovary, pancreas, prostate and heart, and may be up-regulated in cancers of the brain, breast, ovary, and pancreas." (PMID 23644884, 2013).
Charcot-Marie-Tooth neuropathy (2 papers, 2018 to 2019). "HDAC6 inhibition restores tubulin acetylation, rescues disrupted axonal transport, and improves motor functions in the Charcot-Marie-Tooth neuropathy." (PMID 31354911, 2019).
chondrodysplasia (2 papers, 2013 to 2017). "This miRNA has been linked to chondrodysplasia in humans since a mutation in the 3′UTR of HDAC6 was identified within a miR-433 binding site." (PMID 24040378, 2013).
diabetic neuropathy (2 papers, 2021 to 2025). A chronic, pathological complication associated with diabetes mellitus, where nerve damages are incurred due to diabetic microvascular injury involving small blood vessels that supply these nerves, resulting in peripheral and/or autonomic nerve dysfunction. "Considering that HDAC6 inhibitors are being investigated as a treatment for pain caused by peripheral neuropathy in multiple disorders, it would be beneficial to determine how HDAC6 inhibition affects diabetic neuropathy." (PMID 34531721, 2021). "Whether HDAC6 is involved in the development of diabetic neuropathy merits investigation." (PMID 34531721, 2021). "Currently, most studies investigating the activity of HDAC6 on development of painful peripheral neuropathy center on CIPN and CMT, despite diabetic neuropathy showing similar symptoms." (PMID 34531721, 2021).
Duchenne muscular dystrophy (2 papers, 2022 to 2023). Duchenne muscular dystrophy (DMD) is a neuromuscular disease characterized by rapidly progressive muscle weakness and wasting due to degeneration of skeletal, smooth and cardiac muscle. "Inhibition of HDAC6 using TubA improves skeletal muscle disorders in Duchenne Muscular Dystrophy (DMD) by modulating TGF-β signaling." (PMID 38148899, 2023). "Here, authors show that Smad3 acetylation via HDAC6 inhibition reverses Duchenne muscular dystrophy-like symptoms in the mdx mouse model, suggesting a potential therapeutic target for the disorder." (PMID 36402791, 2022).
endotoxemia (2 papers, 2016 to 2020). "In our studies, HDAC6 deletion reduced the production of NO in endotoxemia, which is associated with decreased nitrative stress as evidenced by the reduced nitrotyrosine level in the blood." (PMID 32973784, 2020). "Our data provide direct evidence that HDAC6 is a key regulator of endotoxin-induced iNOS expression in macrophages and iNOS expression in tissues during endotoxemia." (PMID 32973784, 2020). "HDAC6 inhibitors prevented caspase 3 activation in lung tissues with reduced lung edema in a mouse model of endotoxemia." (PMID 27419634, 2016). "We also assessed the protective effects of HDAC6 inhibition against lung inflammatory injury in a mouse model of endotoxemia." (PMID 27419634, 2016). "In Summary, our results suggest that HDAC6 is a key mediator of NO over-production in endotoxemia." (PMID 32973784, 2020). "Our data suggest that HDAC6 contributes to the increased peroxynitrite levels in endotoxemia, which could induce nitrative stress-mediated cellular responses and tissue injury in septic shock." (PMID 32973784, 2020). "HDAC6 regulates LPS-induced iNOS expression in macrophages by modulating STAT1 activation and IRF-1 expression, and facilitates iNOS expression in the tissues during endotoxemia." (PMID 32973784, 2020). "To assess the therapeutic potential of HDAC6 inhibition against endothelial cell injury during acute inflammation, we examined the effects of CAY10603 on caspase-3 activation in a mouse model of endotoxemia." (PMID 27419634, 2016).
fatty liver disease (2 papers, 2023 to 2025). A reversible condition wherein large vacuoles of triglyceride fat accumulate in liver cells via the process of steatosis. "Acting as a deacetylase of FOXO1, HDAC6 is downregulated by binding to S100A11, which increases the acetylation and activity of FOXO1, leading to lipogenesis and activation of autophagy in the liver, thus exacerbating liver steatosis." (PMID 36864020, 2023).
glaucoma (2 papers, 2013 to 2018). Increased pressure in the eyeball due to obstruction of the outflow of aqueous humor. "In the present study we used an in vivo retinal I/R injury model to explore the potential role of HDAC6 in glaucoma." (PMID 30453928, 2018). "Our findings suggest that tubacin exhibits neuroprotective effects after I/R retinal injury, and HDAC6 may be a potential therapeutic target for the retinal neurodegenerative disease of glaucoma." (PMID 30453928, 2018). "Therefore, it greatly interested us whether the HDAC6 inhibitor has neuroprotective properties and its mechanism of action in a glaucoma model." (PMID 30453928, 2018). "No discernible differences in the colocalization of large ASB10-stained structures with ubiquitin or HDAC6 were observed between dermal fibroblasts derived from a normal individual and a patient with primary open-angle glaucoma carrying a synonymous ASB10 mutation." (PMID 23901248, 2013).
infarct (2 papers, 2024 to 2026). "Our present analyses revealed that HDAC6 deletion improved the cardiac infarct size as well as the impaired LVEF, LVFS and E/A ratio in post‐MI mice." (PMID 39232846, 2024). "Findings from the current meta-analysis indicate that pharmacologically inhibiting HDAC6 during the hyperacute phases of AIS confers significant protection, evidenced by smaller infarction sizes and greater recovery of motor function, compared to controls." (PMID 41549345, 2026). "Leave-one-out sensitivity analyses suggested that the effect of HDAC6 inhibition on infarction size was not dependent on data from any single study (Supplement 4)." (PMID 41549345, 2026).
influenza (2 papers, 2020 to 2025). An acute viral infection of the respiratory tract, occurring in isolated cases, in epidemics, or in pandemics; it is caused by serologically different strains of viruses (influenzaviruses) designated A, B, and C, has a 3-day incubation period, and usually lasts for 3 to 10 days. "Since egress of influenza is dependent on formation of liquid-phase membraneless organelles, the regulatory functions of HDAC6 are potentially relevant for vRNP peripheral transport." (PMID 31963544, 2020). "During viral genome replication and egress, HDAC6 once again serves as an important host-cell regulatory factor for influenza." (PMID 31963544, 2020).
injury (2 papers, 2020 to 2022). Damage inflicted on the body as the direct or indirect result of an external force, with or without disruption of structural continuity. "Li found that HDAC6 inhibition blocked the activation of the NF‐κB signalling pathway by suppressing IĸB phosphorylation in LPS‐induced acute lung injury." (PMID 36226351, 2022).
mood disorder (2 papers, 2012 to 2021). A cognitive disorder a disturbance in which the person's mood is hypothesized to be the main underlying feature. "Identification of HDAC6 substrates and related cellular processes in serotonergic neurons associated with the expression of antidepressant-like behavior will bring new insights into the molecular basis of mood disorders." (PMID 22328923, 2012).
motor neuron disease (2 papers, 2019 to 2022). "Summary of 4-PBA and HDAC6 inhibitors demonstrating therapeutic benefit in model systems for early-onset motor neuron diseases." (PMID 36341099, 2022). "As examples of multi-target therapies for motor neuron diseases, we will describe two neuroprotectants that have shown strong in vivo efficacy in different types of motor neuron diseases: 4-phenylbutyrate (4PBA) and inhibitors of histone deacetylase 6 (HDAC6)." (PMID 36341099, 2022).
myeloid leukemia (2 papers, 2021 to 2026). A clonal proliferation of myeloid cells and their precursors in the bone marrow, peripheral blood, and spleen. "Further functional assays conducted in an immunocompetent setting, both ex vivo and in vivo, demonstrated that HDAC6 inhibition sensitized murine myeloid leukemia cells to broad CD8+ T cell activation as evidenced by increased TNFα and CD107a expression." (PMID 41794832, 2026). "Consistently, in a syngeneic murine model, HDAC6 inhibition restricted the growth of myeloid leukemia cells." (PMID 41794832, 2026). "Moreover, pharmacological inhibition of HDAC6 recapitulated this phenotype, leading to RNase T2 upregulation in myeloid leukemia cells." (PMID 41794832, 2026). "Currently, HDAC6 inhibitor ACY-1215 has been reported under clinical trials for different cancer therapy either monotherapy or in combination with other drugs, such as metastatic breast cancer and myeloid leukemia, which suggested targeting HDAC6 may become promising strategy in cancer therapy." (PMID 34868939, 2021).
myocardial infarction (2 papers, 2024). Gross necrosis of the myocardium, as a result of interruption of the blood supply to the area, as in coronary thrombosis. "Experimental myocardial infarction (MI) was created in HDAC6‐deficient (HDAC6−/−) mice and wild‐type (HADC6+/+) by left coronary artery ligation." (PMID 39232846, 2024).
nasopharyngeal carcinoma (2 papers, 2021 to 2025). A carcinoma arising from the nasopharyngeal epithelium. "AT13387, a ground-breaking Hsp90 inhibitor, can restrain Hsp90 molecular chaperone function, downregulate HDAC6 and then increase the acetylation and stabilization of α-tubulin, ultimately suppressing nasopharyngeal carcinoma (NPC) oncogenesis and progression." (PMID 34530730, 2021). "In the present study, we reported that the deacetylation and low expression of transaldolase 1 (TALDO1) mediated by HDAC6 weakened the inhibitory effect of TALDO1 on tumor proliferation and metastasis in nasopharyngeal carcinoma (NPC)." (PMID 41120289, 2025).
osteoporosis (2 papers, 2025). A condition of reduced bone mass, with decreased cortical thickness and a decrease in the number and size of the trabeculae of cancellous bone (but normal chemical composition), resulting in increased fracture incidence. "The use of three of them (HDAC6, IL-8, PPIF) as a diagnostic tool for IBD, combined with osteoporosis, demonstrated high diagnostic efficacy (AUC 0.80)." (PMID 40422241, 2025). "For example, in both IBD and osteoporosis, there is an upregulation of common NET-related genes, namely HDAC6, IL-8, SRC, PPIF, PLCG2, PIK3CD, MAP2K1, and AKT1." (PMID 40422241, 2025).
ovarian clear cell cancer (2 papers, 2019 to 2022). An invasive malignant neoplasm that arises from the ovary and is characterized by a predominance of clear and hobnail malignant epithelial cells. "Recently, it has been described that ARID1A is able to transcriptionally repress histone deacetylase 6 (HDAC6) in ovarian clear cell carcinoma (OCCC); and when loss of ARID1A expression occurs, suppression of HDAC6 is relieved." (PMID 35167193, 2022).
periodontitis (2 papers, 2022 to 2025). An acute or chronic inflammatory process that affects the tissues that surround and support the teeth. "In this study, we demonstrate the role of EGCG as an HDAC6 inhibitor, providing new directions for the clinical prevention and treatment of periodontitis." (PMID 40289388, 2025). "Circ_0138960 promoted LPS‐induced dysfunction in PDLCs by targeting miR‐518a‐5p/HDAC6 axis, which provided novel potential therapeutic targets for periodontitis." (PMID 36444635, 2022). "A previous study found that IL‐1β elevates the mRNA expression of HDAC6 in periodontal ligament fibroblasts, implying its pivotal role in periodontitis pathology." (PMID 36444635, 2022). "Extant studies on the role of HDAC6 in periodontitis have found that overexpression of HDAC6 aggravates the role of LPS in promoting inflammation and apoptosis of periodontal ligament fibroblasts, and inhibits the differentiation of dental pulp stem cells into dentin." (PMID 40289388, 2025). "We confirmed that HDAC6 was elevated in periodontitis sufferers and LPS‐stimulated PDLCs." (PMID 36444635, 2022). "Furthermore, the working mechanism of HDAC6 in periodontitis pathology still needs to be explored." (PMID 36444635, 2022). "Therefore, HDAC6 may be a potential target in the treatment of periodontitis." (PMID 40289388, 2025). "It is suggested that EGCG plays anti‐inflammatory and antioxidative roles by simultaneously regulating the expression of HDAC6 and the Nrf2/HO‐1/NLRP3 signal axis in the present periodontitis cell model." (PMID 40289388, 2025).
pheochromocytoma (2 papers, 2017 to 2019). "Recent studies provided evidence that corticosterone-induced injury in rat adrenal pheochromocytoma PC12 cells can be attenuated by HBOB, an HDAC6 inhibitor, by inhibiting mitochondrial GR translocation and the intrinsic apoptosis pathway." (PMID 29137141, 2017).
prostate tumor (2 papers, 2021). "Distinct HDAC6 inhibition can also sensitize cancer cells to SAHA treatment because the HDAC6-selective inhibitor tubacin was able to increase apoptosis and DNA damage induced by SAHA in LNCaP prostate tumor cells." (PMID 34959719, 2021).
rhabdomyosarcoma (2 papers, 2015 to 2023). A rare aggressive malignant mesenchymal neoplasm arising from skeletal muscle. "Histone deacetylase 6 (HDAC6) is crucial in rhabdomyosarcoma progression." (PMID 37049739, 2023).
serous ovarian cancer (2 papers, 2020 to 2022). "HDAC6 is overexpressed in OC, and HDAC6 upregulation is thought to be associated with poor prognosis and poor chemoresistance in patients with advanced high-grade serous ovarian cancer." (PMID 36505774, 2022). "The promising anti-cancer response of the first-generation HDAC6 catalytic inhibitors continues to be assessed in clinical trials, although its role in high grade serous ovarian cancer is unclear." (PMID 33322608, 2020).
squamous cervical cancer (2 papers, 2021 to 2025). "This study investigated the effect of isoflurane on the proliferation of squamous cervical cancer cells, with focus on histone deacetylase 6 that is closely related to carcinogenesis." (PMID 32833118, 2021). "However, isoflurane promotes the proliferation of squamous cervical cancer cells and increases the expression of histone deacetylase 6 (HDAC6) by activating AKT/mTOR signaling pathway." (PMID 40309242, 2025).